DUSP5 (dual specificity phosphatase 5)
Description:
Dual specificity protein phosphatase; active with phosphotyrosine, phosphoserine and phosphothreonine residues. The highest relative activity is toward ERK1.
Synonyms: HVH3; DUSP
Tractability: Small molecule: it has a high-quality binding pocket. PROTAC: ubiquitination databases record sites on it; a small molecule that binds it is known.
Target class: Phosphatase; Serine/threonine/tyrosine protein phosphatase; Enzyme; Protein Phosphatase
Gene: Protein-coding gene on chromosome 10 (110,497,907 to 110,511,541, forward strand). Ensembl gene ENSG00000138166.
Subcellular location: Nucleus
Pathways (Reactome):
Signal Transduction: Negative regulation of MAPK pathway; RAF-independent MAPK1/3 activation
Gene Ontology:
Molecular function: phosphatase activity; protein binding; protein serine/threonine phosphatase activity; protein tyrosine/serine/threonine phosphatase activity; protein tyrosine phosphatase activity; MAP kinase tyrosine/serine/threonine phosphatase activity
Biological process: dephosphorylation; peptidyl-threonine dephosphorylation; peptidyl-tyrosine dephosphorylation; endoderm formation; ERK1 and ERK2 cascade; MAPK cascade; protein dephosphorylation
Cellular component: nucleoplasm; nucleus
Genetic constraint (gnomAD): Loss-of-function variants: 22 observed, 29.39 expected, observed/expected ratio (o/e) 0.75, 90% interval 0.53 to 1.07. The synonymous counts are far from expectation, so gnomAD's model fits this gene poorly and the ratio says little. Missense variants: 551 observed, 467.03 expected, observed/expected ratio (o/e) 1.18, 90% interval 1.1 to 1.27. Synonymous variants: 270 observed, 202.01 expected, observed/expected ratio (o/e) 1.34, 90% interval 1.21 to 1.48.
Homologues: Orthologues: chimpanzee DUSP5 (99% identical), macaque DUSP5 (99% identical), pig DUSP5 (94% identical), mouse Dusp5 (93% identical), rat Dusp5 (93% identical), dog DUSP5 (93% identical), rabbit DUSP5 (92% identical), guinea pig DUSP5 (91% identical), tropical clawed frog dusp5 (60% identical), zebrafish dusp5 (52% identical). Paralogues in human: DUSP4 (46% identical), DUSP1 (45% identical), DUSP2 (37% identical), DUSP9 (28% identical), DUSP8 (28% identical), DUSP16 (27% identical), DUSP7 (27% identical), DUSP6 (27% identical), SSH1 (24% identical), SSH2 (23% identical), DUSP10 (22% identical), SSH3 (21% identical), and 19 more.
Diseases named in the same sentence as DUSP5 in open-access papers:
DUSP5 is named in the same sentence as 116 diseases in open-access papers, as found by Europe PMC text mining. Sharing a sentence is not in itself a finding about the gene and the disease. The quoted sentences say what the papers report.
colorectal cancer (12 papers, 2016 to 2025). A primary or metastatic malignant neoplasm that affects the colon or rectum. "Downregulation of DUSP5 was also recently reported in colorectal cancer (CRC), and shown to be associated with worse outcome." (PMID 29379130, 2018). "In colorectal cancer, low DUSP5 expression has been linked to poor prognosis." (PMID 40558895, 2025). "LncRNA CRNDE promotes colorectal cancer cell proliferation by inhibiting the expression of DUSP5 and CDKN1A." (PMID 33522895, 2021). "Our results suggest that DUSP5 plays a limited role in regulating ERK signalling associated with the growth of colorectal tumours, but that methylation the DUSP5 gene promoter can serve as an additional means of identifying CIMP-high colorectal cancers." (PMID 29379130, 2018). "On the contrary, DUSP5 is found to be a tumor-suppressive factor by inactivation of ERK in gastric cancer, colorectal cancer and so on." (PMID 38872157, 2024). "However, the mechanisms underlying DUSP5 loss in this disease, and whether its loss contributes to aberrant ERK signalling or the initiation and/or progression colorectal cancers has not been established." (PMID 29379130, 2018).
melanoma (10 papers, 2017 to 2025). A malignant, usually aggressive tumor composed of atypical, neoplastic melanocytes. "As increased DUSP1 and DUSP5 expression occurred with corin treatment of BRAFi-R melanoma cells, we sought to establish baseline levels of DUSPs in BRAF-sensitive and BRAF-resistant melanoma cell lines." (PMID 38300709, 2024). "Crucially, we observed a rapid downregulation of DUSP6, followed by DUSP5 induction at later time points, in both melanoma genetic subtypes, confirming the observations made with RocA." (PMID 39436655, 2024). "In addition, p38 MAPK activity was shown to be inhibited in all NRAS-mutant melanoma cell lines following corin treatment, with associated increases in DUSP1 and DUSP5 expression." (PMID 38300709, 2024). "In addition, circ_0002770 contributed to the progression of melanoma via interacting with miR-331-3p and elevating DUSP5/TGFBR1 expression." (PMID 34056112, 2021). "Our RNA-seq analyses showed significant upregulation of not only EGR1 but also DUSP5 and DUSP6 expression in response to eIF4Fi in both melanoma genetic contexts." (PMID 39436655, 2024). "A further analysis of MAPK regulatory genes showed that mRNAs for several DUSPs-DUSP1 DUSP5, DUSP8, DUSP10 and DUSP14-were upregulated in intrinsically MAPKi-resistant melanoma cell line." (PMID 35999349, 2022). "Absence of mutation of DUSP5 and DUSP6 reported in thyroid cancers as well as in melanomas support the hypothesis that these phosphatases have no tumor suppressor role in this type of carcinoma." (PMID 28910386, 2017).
cardiac hypertrophy (9 papers, 2014 to 2025). "DUSP5 has previously been implicated as a regulator of ERK1/2 signaling in response to pathological cardiac hypertrophy and fibrosis." (PMID 29018280, 2017). "Besides vascular anomalies, DUSP5 has also been implicated as a target for cardiac hypertrophy and immune conditions." (PMID 25519881, 2014). "Histone deacetylase inhibitors and DUSP5 participate in an integral regulatory signaling circuit that controls cardiac hypertrophy." (PMID 27936095, 2016). "Recent data suggests that small molecule histone deacetylase (HDAC) inhibitors suppress cardiac hypertrophy via inhibition of DUSP5." (PMID 25519881, 2014). "Dusp5 plays an important role in cardiac hypertrophy, which regulates the ERK1/2signaling pathway." (PMID 41296393, 2025). "DUSP5 has also been shown to regulate cardiac fibroblast proliferation and cardiac hypertrophy." (PMID 38314139, 2023). "Cardiomyocytes, the primary cell type involved in cardiac hypertrophy, show differential effects on ERK signaling in the nucleus and cytoplasm; in that nuclear ERK1/2 activation is suppressed in a DUSP5-dependent manner, while cytosolic ERK1/2 activation is maintained under these same conditions." (PMID 25519881, 2014).
thyroid cancer (9 papers, 2014 to 2025). "In thyroid cancer, increased DUSP5 and DUSP6 MAPK phosphatase expression was associated with higher ERK activity in BRAF-mutant tumors." (PMID 39436655, 2024). "Furthermore we confirmed in our five BRAF-mutated human thyroid carcinoma cell lines that DUSP5 and DUSP6 induction was blocked by MEK inhibition, using a highly potent and selective MEK inhibitor namely AZD6244." (PMID 28910386, 2017). "In contrast to all the studies above, a recent work showed that DUSP5 is overexpressed in BRAF-mutant thyroid cancer cells and that DUSP5 KD reduces proliferation and migration." (PMID 40943262, 2025). "We also report here for the first time the consequences of DUSP5 inactivation in human thyroid cancer cells." (PMID 28910386, 2017). "Silencing of DUSP5 or DUSP6 phosphatases by siRNA reduced the neoplastic properties of BRAFV600E-thyroid carcinoma cell lines." (PMID 28910386, 2017). "We investigated the proliferative effect of DUSP5 and DUSP6 silencing in two BRAFV600E mutated human thyroid carcinoma cell lines (BCPAP and 8505c)." (PMID 28910386, 2017). "These include C8orf4, also known as thyroid cancer 1 (TC-1), DUSP5, involved in ERK1/2 pathway attenuation, and ARG2, whose over-expression has been associated with the thyroid cancer pathogenesis." (PMID 24810336, 2014). "Furthermore, DUSP5, known for its overexpression in human thyroid carcinoma (TC) tissues, plays a pivotal role in fostering TC cell metastasis and anchorage-independent growth." (PMID 38570607, 2024). "Moreover, we unearthed that the DUSP5 was upregulated in various cancers, including invasive breast carcinoma, cholangiocarcinoma, thyroid carcinoma, and esophageal carcinoma." (PMID 38872157, 2024). "In thyroid cancer cells, rebound of ERK signaling upon BRAFV600E treatment may be caused by downregualtion of ERK phosphatase DUSP5 and increased HER3 expression." (PMID 26023796, 2015). "For that purpose, we studied the MAPK pathway activation, the expression and regulation of DUSP5 and DUSP6, and the consequences of their inactivation in thyroid cancer cell lines." (PMID 28910386, 2017). "We found out that DUSP5 and DUSP6 are overexpressed in human thyroid carcinomas and are surrogate markers of MAPK pathway activation." (PMID 28910386, 2017). "Finally, DUSP5 and DUSP6 silencing reduced the cell migration and invasion capacities of two BRAFV600E thyroid cancer cell lines, thus suggesting a pro-tumorigenic role of these phosphatases in PTC." (PMID 28910386, 2017). "Using two BRAFV600E thyroid carcinoma cell lines (BCPAP and 8505c), the same authors showed that genetic inhibition of DUSP5 and DUSP6 did not affect cell proliferation or ERK1/2 phosphorylation, while reducing cell migration and invasion." (PMID 40943262, 2025). "DUSP5 and DUSP6 have no tumor suppressor properties in two BRAFV600E thyroid carcinoma models, but instead they seem to have a protumorigenic role on thyroid carcinogenesis." (PMID 28910386, 2017).
diabetes (7 papers, 2015 to 2025). "Protein tyrosine phosphatases (PTPs) are drug targets for a wide range of diseases, ranging from vascular anomalies and cancer (DUSP5) to diabetes (PTP1B)." (PMID 28569147, 2017). "Additionally, diabetes‐induced HDAC3 activation inhibits DUSP5 expression by deacetylating histone H3 in the primer region of DUSP5." (PMID 40497340, 2025). "Nevertheless, DUSP5 is a critical drug target for vascular-related diseases, and more broadly, MAPKs and their DUSP partners are involved in cell signaling that is directly involved in a wide range of diseases, including cancer, diabetes, and autoimmune disorders." (PMID 26286528, 2015). "Protein tyrosine phosphatases (PTPs) like dual specificity phosphatase 5 (DUSP5) and protein tyrosine phosphatase 1B (PTP1B) are drug targets for diseases that include cancer, diabetes, and vascular disorders such as hemangiomas." (PMID 28569147, 2017). "Furthermore, it is worth exploring whether the KO of Dusp5 reduces BBB permeability and neurodegeneration in aging, hypertension, or diabetes as we observed in other models." (PMID 37588944, 2023).
gastric cancer (7 papers, 2018 to 2025). A primary or metastatic malignant neoplasm involving the stomach. "Consistent with this putative tumour suppressor role, DUSP5 expression is downregulated in prostate and gastric cancers where loss of expression is associated with poor prognosis." (PMID 29379130, 2018). "In gastric cancer cells as well as colon cancer cells, overexpression of DUSP5 significantly promoted apoptosis." (PMID 37766214, 2023). "In gastric cancer, DUSP5 downregulation was reported to correlate with promoter CpG island methylation, and its re-expression in gastric cancer cell lines reduced nuclear p-ERK levels and cell growth." (PMID 29379130, 2018). "However, upregulated DUSP5 inhibited the process of EMT in gastric cancer and hepatocellular carcinoma through MAPK pathway, and the cells showed a reduced migration ability and increased apoptosis." (PMID 32867783, 2020). "Promoter methylation of DUSP5 in these cancers may be a passenger event, which differs from its role in gastric cancer cells." (PMID 29379130, 2018). "For example, the oncogenic lncRNA linc01503 in gastric cancer interacts with zeste homolog 2 (EZH2) and lysine (K)-specific demethylase 1A (LSD1) enhancers, targeting the promoter regions of dual-specificity phosphatase 5 (DUSP5) and cyclin-dependent kinase inhibitor 1A (CDKN1A)." (PMID 41229433, 2025).
ovarian carcinoma (7 papers, 2005 to 2024). A malignant neoplasm originating from the surface ovarian epithelium. "DUSP5, a member of the dual-specificity phosphatase family dephosphorylates both tyrosine and serine/threonine residues and is repressed in several cancers, including breast, lung, and ovarian cancers." (PMID 38926346, 2024). "Dual Specificity Phosphatase 5 (DUSP5) is tumor suppressor in ovarian cancer." (PMID 33614471, 2020). "G9a depletion restored a cohort of tumor suppressor genes including E-cadherin, DUSP5, SPRY4, and PPP1R15A in ovarian cancer." (PMID 27531902, 2016). "Importantly, microarray and quantitative RT-PCR analysis revealed that G9a regulates a cohort of tumor suppressor genes including CDH1, DUSP5, SPRY4, and PPP1R15A in ovarian cancer." (PMID 25115793, 2014). "Finally, we observed that the DEGs DUSP5 (r = 0.487, p < 0.0001), CXCL2 (r = 0.355, p < 0.0001), and IL-6 (r = 0.401, p < 0.0001) were amongst some of the top correlative genes with AREG in the TCGA ovarian cancer cohort, adding a further degree of clinical relevance to our NanoString analysis." (PMID 38831884, 2024).
prostate carcinoma (7 papers, 2016 to 2021). A carcinoma that arises from epithelial cells of the prostate gland. "Loss of DUSP5 was associated with inferior clinical outcomes in patients with gastric and prostate cancer and re-expression of DUSP5 shrunk cell proliferation indices in various cancer cell lines." (PMID 34360545, 2021). "We have found that the nuclear ERK-selective phosphatase DUSP5 is downregulated in colorectal tumours and cell lines, as previously observed in gastric and prostate cancer." (PMID 29379130, 2018). "Moreover, low Dusp5 expression was shown to be an adverse prognostic factor in patients with gastric/prostate cancer." (PMID 26967242, 2016). "Notable genes in the predicted pathway included ATF3, JUNB, KLF6, NR4A2, ZFP36, DUSP5 and NEDD9, as well as STAT3 and IRF1 as novel upstream regulators, and SELE, CXCL1 and CXCL2 as novel downstream targets of NFκB in prostate cancer." (PMID 27078000, 2016). "Our predicted NFκB pathway suggested 8 novel genes which were found to be highly down-regulated in lethal prostate cancer and highly functionally related to NFκB, namely ATF3, CXCL2, DUSP5, JUNB, NEDD9, SELE, TRIB1, and ZFP36." (PMID 27078000, 2016). "All of these genes were down-regulated in patients who had disease that relapsed after a prostatectomy, which could be the result of negative feedback loops in lethal prostate cancer that turn off important cancer regulators, such as ZFP36, DUSP5, and ATF3." (PMID 27078000, 2016).
breast cancer (6 papers, 2015 to 2026). A primary or metastatic malignant neoplasm involving the breast. "To assess the impact of the 3LBNC on gene expression, we evaluated the levels of E-cadherin, JUNB, and DUSP5, three genes associated with breast cancer." (PMID 40558895, 2025). "Finally, we evaluated DUSP5 expression due to its reported association with paclitaxel (PTX) resistance in basal-like breast cancer." (PMID 40558895, 2025). "Upon DUSP5 overexpression, both GLO1-depleted cells showed a decreased migratory capacity thus functionally linking DUSP5 regulation occurring under MG stress with pro-metastatic features in breast cancer cells." (PMID 30674353, 2019). "DUSP5 overexpression decreases the migratory capacity of GLO1-depleted breast cancer cells." (PMID 30674353, 2019).
glioma (5 papers, 2018 to 2025). A benign or malignant brain and spinal cord tumor that arises from glial cells (astrocytes, oligodendrocytes, ependymal cells). "In another study, DUSP5 emerged as a possible oncosuppressor in glioma by counteracting the protumoural role of the p68 RNA helicase, which had been previously demonstrated to be overexpressed in glioma and to be correlated with poor overall survival." (PMID 40943262, 2025). "DUSP5 negatively regulates the ERK proliferation pathway; thus, overexpression of DDX5 observed in gliomas causes hyperactivation of ERK through downregulation of DUSP5, promoting cancer proliferation." (PMID 35954483, 2022). "Published studies have shown that DDX5 enhances glioma cells invasion by negatively regulating DUSP5." (PMID 32694946, 2020). "Furthermore, DUSP5 acts as a negative regulator of glioma cell motility and the ERK signaling pathway." (PMID 39940838, 2025). "Moreover, both p68 inhibition and DUSP5 overexpression led to a decrease of ERK1/2 phosphorylation and the proliferation, invasion, and migration of the glioma cell line U87." (PMID 40943262, 2025). "The use of a FAK inhibitor in glioma cells increases expression of DUSP1 and DUSP5, suggesting the existence of a negative feedback loop." (PMID 29022062, 2018).
Insulin resistance (5 papers, 2013 to 2022). Increased resistance towards insulin, that is, diminished effectiveness of insulin in reducing blood glucose levels. "It was reported that DNA methylation of exon 2 of dual specificity phosphatase 5 (DUSP5) in IUGR rats caused an increase in mRNA expression, which led to insulin resistance by regulating Ras-MAPK signaling pathway activity." (PMID 32139393, 2020). "In addition, plasma glucose and HbA1C levels were similar and in the normal ranges in 9–12 weeks old Dusp5 KO in comparison with WT control rats, suggesting KO of Dusp5 unlikely induces insulin resistance or hyperglycemia in this study." (PMID 31960618, 2020). "Loss of DUSP5 function studies in rodent models of diet-induced obesity would highlight the role for this phosphatase in the regulation of ERK signaling, adipose tissue inflammation and insulin resistance." (PMID 29018280, 2017). "KO of Dusp5 did not alter body and organ (brain and kidney) weights and did not induce insulin resistance or hyperglycemia." (PMID 31960618, 2020).
Obesity (5 papers, 2014 to 2025). Accumulation of substantial excess body fat. "DUSP5 gene expression proportionally increased with increased obesity and this positively correlated to an increase in TNFα." (PMID 29018280, 2017). "As obesity develops, DUSP5 mRNA expression rises with an increase in TNFα expression." (PMID 40093618, 2025). "Moreover, DUSP5 mRNA expression increased during obesity development concomitant to increases in TNFα expression." (PMID 29018280, 2017). "Thus, DUSP5 potentially acts as an endogenous regulator of adipose tissue inflammation; although its role in obesity-mediated inflammation and insulin signaling remains unclear." (PMID 29018280, 2017). "Similar to TNFα expression, DUSP5, an ERK1/2 specific phosphatase, increased with the development of obesity." (PMID 29018280, 2017). "While our findings suggest that DUSP5 potentially regulates ERK-mediated activation of obesity-induced inflammation, studies examining DUSP5 in obesity-mediated metabolic dysfunction have yet to be performed." (PMID 29018280, 2017). "We report that DUSP5, an ERK1/2 phosphatase, was induced in epididymal white adipose tissue (WAT) in response to diet-induced obesity." (PMID 29018280, 2017). "Functional redundancy amongst the nuclear specific DUSPs, which in addition to DUSP2 include DUSP1, DUSP4 and DUSP5, may also be a contributing factor in DUSP2 not playing a unique role in obesity-associated WAT inflammation." (PMID 25375135, 2014).